MMP3 (matrix metallopeptidase 3)
Diseases named in the same sentence as MMP3 in open-access papers (continued):
Sharing a sentence is not in itself a finding about the gene and the disease.
adenoma (5 papers, 2003 to 2023). A neoplasm arising from the epithelium. "The analysis of colonic adenomatous nodes revealed low expression of all the explored acute colitis-associated key genes: the expression levels of C3, Tyrobp, Mmp3, Mmp9, and Timp1 in adenoma tissue were 26.3, 3.4, 20.8, 11.9, and 27.7 times lower than those in the samples with acute colitis." (PMID 36901742, 2023). "Lièvre examined gene promoter polymorphism mainly in MMP-3, but also in MMP-7 and MMP-1 in patients with adenomas." (PMID 38203373, 2023). "The experimental results confirmed a close and strong correlation between MMP-3, MMP-1 polymorphisms, and adenomas." (PMID 38203373, 2023). "The analysis revealed a significant association between MMP-3-1612 ins/del A, MMP-1-1607 ins/del G polymorphism, and small adenomas; also, adenomas were associated with the combined genotype 2G/2G-6A/6A." (PMID 34944846, 2021). "The authors suggested that only the study MMP-3 and MMP-1 gene promoter polymorphisms had potential roles in the development of adenomas from normal colon epithelial cells or in the earliest steps of CRC." (PMID 34944846, 2021). "In addition to MMP-7 expression, 60–65% of Min adenomas express MMP-2 and MMP-10 (stromelysin-2) and 50% express MMP-3 and MMP-13 (collagenase) with expression limited to the stroma surrounding the adenoma." (PMID 12778076, 2003).
astrocytoma (5 papers, 2010 to 2024). "Similar results were obtained in astrocytomas: specifically, in the genes MMP3, MMP8, MMP10, TIMP2, and TIMP4." (PMID 38474106, 2024). "MMP-3 plays a crucial role in the insidious invasiveness of astrocytoma." (PMID 20492722, 2010).
coronary atherosclerosis (5 papers, 2006 to 2021). Atherosclerosis of the coronary vasculature. "Another author found that patients with CAD had higher MMP‐9 and TIMP‐1 plasma levels but a lower TIMP‐2 level, also both increased MMP‐9 and TIMP‐ 1 plasma levels in premature coronary atherosclerosis patients, but with lower MMP‐3 and TIMP‐2 levels." (PMID 33381894, 2021). "Our study presents an interesting opportunity for the potential application of RhoA/ROCK inhibitors or transplantation approach using MMP3-overexpressed MSCs in patients with coronary atherosclerosis or post coronary angioplasty." (PMID 27126736, 2016).
epilepsy (5 papers, 2011 to 2024). A brain disorder characterized by episodes of abnormally increased neuronal discharge resulting in transient episodes of sensory or motor neurological dysfunction, or psychic dysfunction. "The serum lncRNA ILF3AS1 expression levels were higher in children with epilepsy and were associated with higher levels of MMP3 and MMP9 as well as lower levels of miRNA-212 than those in the control group." (PMID 39268188, 2024). "In summary, we found that lncRNA ILF3AS1, miRNA-212, MMP3, and MMP9 have predictive and diagnostic powers for epilepsy, with AUC values of 0.656, 0.965, 0.659, and 0.738, respectively." (PMID 39268188, 2024). "MMP3 can be induced by the pro-inflammatory cytokine IL-1β and is regulated by miR-155, suggesting a possible strategy to prevent epilepsy via reduction of inflammation." (PMID 30031401, 2018). "We have examined the levels of MMP-3 in 124 MG patients and compared them to 59 multiple sclerosis (MS) patients, 74 epilepsy patients, 33 acute stroke patients, and 90 healthy controls." (PMID 22312479, 2011). "Multiple studies have explored the associations between miRNA-212 and epilepsy, but very few studies have explored the association between the lncRNA ILF3AS1 and epilepsy, considering that miRNA-212 is targeted by lncRNA ILF3AS1, causing boomback effects on MMP3 and MMP9." (PMID 39268188, 2024). "We aimed to assess the serum expressions of the lncRNAs ILF3AS1, MMP3, and MMP9 along with microRNA-212 (miRNA-212) as predictive biomarkers in children with epilepsy; we also assessed their correlations with magnetic resonance imaging (MRI) findings." (PMID 39268188, 2024). "The results showed significantly higher levels of lncRNAs ILF3AS1, MMP3, and MMP9 as well as lower levels of miRNA-212 in children with epilepsy compared to the controls." (PMID 39268188, 2024). "Moreover, the serum levels of the metalloproteinases (MMP3 and MMP9) were elevated in the epilepsy group compared to the control group with significant differences." (PMID 39268188, 2024). "MMP3 and MMP9 expressions are known to be promoted by ILF3AS1 overexpression, leading to the hypothesis that MMP inhibitors could be reliable treatments for epilepsy." (PMID 39268188, 2024).
keratoconus (5 papers, 2016 to 2023). A degenerative, structural disorder of the eye, characterized by a cone-shaped protrusion of the cornea. "In fact, proinflammatory cytokines (IL-1, IL-6, TNF-α, and TGF-β), oxidative stress, or degradation of collagens by metalloproteases (MMP-1, MMP-3, and MMP-9) has been implicated in keratoconus pathophysiology." (PMID 35075374, 2022). "Further cyclical mechanical experiments revealed that several protease genes (including MMP1, MMP3, CTSD and CTSK) can be induced by stretch, indicating the inductive role of mechanical stretch in keratoconus pathogenesis." (PMID 35821117, 2022). "Partly in line with these results, increased tear levels of MMP-1, MMP-3, MMP-7, MMP-9, and MMP-13; IL-4, IL-5, IL-6, and IL-8, and TNF-α, -β were found in keratoconus." (PMID 26881061, 2016). "Further cyclical mechanical experiments on human corneal stromal cell lines demonstrated that mechanical stretch prompted the expression of several protease genes, including MMP1, MMP3, CTSD and CTSK, implying the activating effect of mechanical stretch on proteases during keratoconus progression." (PMID 35821117, 2022). "Elevated levels of interleukin- (IL-) 1b, IL-4, IL-5, IL-6, IL-8, and IL-17; tumor necrosis factor (TNF)-α, -β; interferon- (IFN-) γ; matrix metalloproteinase- (MMP-) 1, MMP-3, MMP-7, MMP-9, and MMP-13; Cathepsin B; and Lipocalin-1 have been found in the tears of patients with keratoconus." (PMID 26881061, 2016).
liver cancer (5 papers, 2015 to 2024). An epithelial or non-epithelial malignant neoplasm that arises from the liver. "Liver cancer biomarkers were assessed in all groups through COX-2, MMP-3, HSP90, VEGF (vascular endothelial growth factor), and Interleukin-6 (IL-6)." (PMID 39281276, 2024). "Interestingly, in this study, bufalin also could increase the expression of MMP3, an essential protein in regulating cell migration, which is in contrast to another study that showed bufalin reduced the levels of MMP2/9 in liver cancer HCCLM3 and HepG2 cells." (PMID 37860119, 2023).
lung diseases (5 papers, 2013 to 2022). "MMP3 cannot only synergistically degrade the extracellular matrix, but also accelerate the decomposition of the basement membrane of pulmonary blood vessels, and participate in the remodeling of pulmonary blood vessels, playing an indispensable role in the occurrence and prognosis of lung diseases." (PMID 35912246, 2022). "Therefore, the aberrant expression of MMP-3 may be instrumental in promoting lung diseases." (PMID 35784288, 2022).
multiple sclerosis (5 papers, 2013 to 2024). A progressive autoimmune disorder affecting the central nervous system resulting in demyelination. "MMP-3 is reported to be associated with bone resorption, fat mass and muscle wasting caused by nerve fibre demyelination and multiple sclerosis." (PMID 36282293, 2023). "For example, increased levels of MMP-2 and -9 have been associated with BBB failure in multiple sclerosis, while MMP-3 and -13 were increased in the brains of subjects with HAND." (PMID 37496706, 2023).
polyarthritis (5 papers, 2016 to 2024). "Expression of miR-223 is increased in polyarthritis and has been correlated with matrix metalloproteinase-3 (MMP3)." (PMID 31641939, 2020). "The IL-6-dominant subset had a more severe polyarthritis and higher serum levels of matrix metalloproteinase (MMP-3), whereas the IL-18-dominant subset was more prone to develop MAS." (PMID 27999545, 2016). "QLY and XYQLY eased polyarthritis in AIA rats after repeated doses, which reflected in reduced inflammation and bone degradation and downregulated p-p65, MMP3, and TLR4 expressions in joints." (PMID 35509625, 2022).
psoriatic arthritis (5 papers, 2011 to 2019). Joint inflammation associated with psoriasis. "It has been shown that MMP3 correlates with disease activity indices even in psoriatic arthritis (PsA)." (PMID 31440510, 2019). "In this analysis of psoriatic arthritis, patients who favorably responded to adalimumab significantly reduced levels of matrix metalloproteinase-3 (MMP-3) and MMP-13, and a trend towards lower levels of von Willerbrand factor, IL-1 and IL-6, was found." (PMID 21876832, 2011). "A recent systematic review identified four candidate serum-soluble bone-turnover biomarkers (dickkopf-1, Dkk-1; macrophage-colony stimulating factor, M-CSF; matrix metalloproteinase-3, MMP-3; osteoprotegerin, OPG) showing possible association with psoriatic arthritis (PsA)." (PMID 28934972, 2017). "In addition to RA, MMP-3 glycans may be altered in other disease conditions that increase serum MMP-3, such as psoriatic arthritis, reactive arthritis, steroid use, and polymyalgia rheumatica, requiring measurement of ACG/Jacalin under various situations." (PMID 27209430, 2016).
sarcopenia (5 papers, 2012 to 2025). Progressive decline in muscle mass due to aging which results in decreased functional capacity of muscles. "A clinical study involving 100 patients with rheumatoid arthritis-associated sarcopenia showed that high blood MMP3 levels were independently associated with sarcopenia." (PMID 40008206, 2024). "Other risk factors were MMP3 levels, age, disease severity, and joint dysfunction, whilst RA treatment was associated negatively with the onset of sarcopenia." (PMID 33566325, 2021). "Consistent with this, both neurotrypsin and matrix metalloproteinase-3 (MMP-3) cleave agrin, and increased cleavage (or increased levels of cleavage fragments) has been proposed to promote age-related muscle decline, called sarcopenia." (PMID 23056392, 2012). "In a subsequent study, univariate analysis observed that male sex, old age, glucocorticoid use > 5 mg/day, high levels of MMP3, and higher disability evaluated by the Health Assessment Questionnaire (HAQ) were associated with sarcopenia (defined by AWGS) development at 2 years in RA patients." (PMID 33566325, 2021). "Nevertheless, some authors have found a relationship between MMP3, PAI-1, and FAS and skeletal muscle senescence, highlighting the need to further investigate the role of these factors in sarcopenia." (PMID 40564069, 2025). "Early analysis showed an independent correlation between sarcopenia (defined by the AWGS definition) and high body fat mass, low BMI, and high matrix metalloproteinase-3 (MMP3)." (PMID 33566325, 2021).
skin cancer (5 papers, 2006 to 2026). "Tsukifuji and colleagues reported an over-expression of MMP-1, MMP-2, and MMP-3 in skin cancer (16 Ak, 6 AK with SCC, and 15 SCC)." (PMID 16893473, 2006). "Samples of perilesional skin and different skin tumors (viral warts and different stages of cSCC) were analyzed for hyperactivation of the MEK-ERK pathway by staining for pERK1/2, activation of epidermal MMP1 and MMP3 expression, as well as stromal upregulation of GM-CSF." (PMID 35174094, 2022).
spondyloarthritis (5 papers, 2008 to 2025). "The rapid decrease ofserum MMP-3 level after TNF blocking therapy is in line with earlier observations inpatients with spondyloarthritis (SpA)." (PMID 20844595, 2010). "In contrast, adalimumab-treated spondyloarthritis (AS and non-radiographic axial spondyloarthritis) patients had a significant decrease of VEGF (P < 0.001) and MMP-3 (P = 0.022) after 36 to 52 weeks of therapy." (PMID 18945353, 2008). "Rising levels of BALP and the negative correlation between MMP-3 and BALP in spondyloarthritis patients with TNF-α blocker treatment indicate that new bone formation in AS occurs if inflammation is successfully treated and might be part of a healing process." (PMID 18945353, 2008).
type 1 diabetes (5 papers, 2015 to 2024). "In the present study in individuals with type 1 diabetes, we showed that serum levels of MMP-3 were positively associated with cfPWV." (PMID 29070037, 2017). "Our study is the first to show an independent association between serum MMP-3 and cfPWV in individuals with type 1 diabetes, after (extensive) adjustment for potential confounders." (PMID 29070037, 2017). "Nevertheless, the study indicated an association among MMP-3 and MMP-10, and macrovascular and microvascular complications in patients with type 1 diabetes." (PMID 33371324, 2020). "In patients with type 1 diabetes followed for a median of 12 years, higher plasma MMP-2 levels are associated with incident CVD and higher plasma MMP-1, MMP-2, MMP-3 are associated with all-cause mortality." (PMID 28446168, 2017). "In this study with type 1 diabetic patients, plasma MMP-2, MMP-3, MMP-10 and TIMP-1 levels are associated with macro- and microvascular complications and these associations were largely independent of LGI and ED." (PMID 25848912, 2015).
ulcer (5 papers, 2010 to 2023). "As such, this study surveyed if the H. pylori dupA genotype and certain SNP genotypes of MMP-3, MMP-7, MMP-9, TIMP-1, and TIMP-2 predispose H. pylori-infected Taiwanese patients to ulcer risks." (PMID 20707923, 2010). "In addition, the upregulation of MMP-3 in inflammatory cells of ulcer tissues is similar to TIMP-1." (PMID 22645431, 2012). "This study investigated if the H. pylori dupA genotype and certain host single nucleotide polymorphisms (SNPs) of matrix metalloproteinases (MMPs) and their inhibitors (TIMPs), including MMP-3, MMP-7, MMP-9, TIMP-1 and TIMP-2, might correlate with ulcer risk of H. pylori-infected Taiwanese patients." (PMID 20707923, 2010). "SJHY formula also could adjust their metabolism in wound healing fibroblasts, as well as the expression of MMP-3 and TIMP-1 in ulcer tissues of diabetic rats." (PMID 29378560, 2018). "Moreover, the gastric mucosa at the ulcer site also has significantly higher expression of MMP-3 than those in the antrum, which suggests MMP-3 is abundant in the ulcer part, and this may help the process of re-epithelialization and contribute to wound healing." (PMID 20707923, 2010). "Moreover, in the NSAID-related group and the combined H. pylori-infection and NSAID-use group, MMP-3, MMP-9, and TIMP-1 expression over inflammatory cells of the lamina propria of ulcer tissues were higher than in nonulcer tissues (P < 0.05)." (PMID 22645431, 2012).
ulcerative colitis (5 papers, 2015 to 2024). An inflammatory bowel disease involving the mucosal surface of the large intestine and rectum. "Protein-protein interaction analysis has underscored the significance of hub genes, notably Stat3, Il1b, Mmp3, and Lgals3, in the progression of ulcerative colitis." (PMID 38308210, 2024). "Ulcerative colitis is a chronic inflammatory bowel disease in which the level of MMP3 and MMP9 is increased in human patients." (PMID 36552443, 2022). "Mmp3, Mmp10, and Mmp13 mRNA levels were significantly upregulated in ulcerative colitis and colorectal adenocarcinoma compared with the levels of normal cohorts." (PMID 25742789, 2015).
vasculitis (5 papers, 2012 to 2024). "MMP-3 levels were significantly higher in all groups of patients who suffered from vasculitis in comparison to the Control Group." (PMID 33664330, 2021). "In HO-1−/− mice, enhanced serum ICAM-1, E-selectin, and MMP-3 levels indicate the presence of vasculitis and systemic inflammation." (PMID 23285041, 2012). "However, MMP-3 levels were significantly lower in the control group in comparison to the groups with vasculitis (p < 0.001)." (PMID 33664330, 2021). "Although the underlying mechanisms remain unclear, previous studies reported that glucocorticoids increased serum MMP-3 levels and also that glucocorticoids were associated with elevated CXCL13 levels in multiple diseases, including vasculitis." (PMID 33743769, 2021). "MMP-3, CXCL-13, C5a can be potential markers in differentiating an active phase of vasculitis from other pathologies." (PMID 33664330, 2021). "Receiver operating characteristic curve analysis (ROC) revealed a good ability of MMP-3, CXCL-13 and C5a in distinguishing active vasculitis (Active Group) from the Control Group (AUC > 0.8)." (PMID 33664330, 2021). "In summary, MMP-3, CXCL-13, C5a can be helpful in differentiating an active phase of vasculitis from other pathologies." (PMID 33664330, 2021). "Receiver operating characteristic curve analysis (ROC) was used to evaluate MMP-3, CXCL-13 and C5a as markers of the different phases of vasculitis." (PMID 33664330, 2021). "The following potential proteases for the different CKD aetiologies were identified: ADPKD (MMP7), MCD (CTSB, CTSD, CTSE, MEP1A, MMP7, PGA3), MGN (MMP3, MMP7, MMP9, MMP13, MMP14), IgAN (MMP7), FSGS (MMP3, MMP7), vasculitis (PGA3), nephritis (MMP7, MMP9), nephrosclerosis (MMP7), and DKD (MMP9)." (PMID 32427855, 2020). "The lack of a significant correlation between MMP-3 and kidney function in patients with active disease can be attributed to the fact that high-grade inflammation, which accompanies active vasculitis, overlaps on slightly expressed inflammation resulting from CKD." (PMID 33664330, 2021).
amyloid (4 papers, 2022 to 2025). "Data analyses showed that while tau pathology is strongly associated with MMPs (MMP-2,-3,-10) and TIMPs (TIMP-1,-2,-3,-4), amyloid pathology is only associated with MMP-3 and TIMP-4 levels." (PMID 38935232, 2025). "In contrast, amyloid-positivity was only significantly associated with reduced levels of MMP-3 and TIMP-4, and for these markers tau-positivity had a larger effect." (PMID 37221606, 2023). "For example, upregulated MMP-3 levels were found in the cortex of AD-like amyloidosis transgenic rat models, and the concentration of MMP-3 and levels of total and phosphorylated tau positively correlate in the cerebrospinal fluid (CSF) of AD patients." (PMID 35573838, 2022). "Additionally, in AD brain, Mmp3 expression is high in astrocytes around neurofibrillary tangles and amyloid plaques." (PMID 37759245, 2023). "Especially, our results suggest that sex-specific effects of these MMP-3 and TIMP-4 on amyloid pathology should be studied further." (PMID 37221606, 2023). "In addition, MMP-3 protein concentration negatively correlated with the score in Mini-Mental State Examination (MMSE) and positively with an occurrence of amyloid deposits and NFTs." (PMID 38935232, 2025). "Our findings show sex-specific effects of MMP-3 and TIMP-4 on amyloid pathology." (PMID 37221606, 2023).
aortic aneurysm (4 papers, 2004 to 2024). A ruptured aneurysm located in the wall of the proximal portion of the descending aorta proceeding from the arch of the aorta. "Numerous studies have reported high levels of MMP-3 in atherosclerotic plaques in any kind of aortic aneurysm." (PMID 19886986, 2009). "The enriched expression of MMP3 in VSMCs were previously shown to be regulated by Piezo1 activation in VSMC of aortic aneurysm, suggesting that the old and AngII‐treated young cells are associated with dysfunction in mechanosensory behaviors and high risk of cardiovascular disease development." (PMID 37941511, 2024). "Among a wide range of MMPs tested, only MMP-3 was over-expressed in the aortic aneurysm samples." (PMID 15482602, 2004). "In agreement with this, several studies reported an increased expression and activity of MMP-1, MMP-2, MMP-3, MMP-9, and MMP-12 in aortic aneurysm tissues." (PMID 35456498, 2022).